CD38 (CD38 molecule)
Diseases named in the same sentence as CD38 in open-access papers (continued):
Sharing a sentence is not in itself a finding about the gene and the disease.
benign tumor (1 paper, 2016). "In the present investigation, significantly high percentage of CD19+ CD24+ CD38+ Bregs was seen in the PMBCs of IBCa patients compared with that in benign tumor patients or healthy individuals." (PMID 27762298, 2016). "We confirmed that PD-L1 was higher on CD19+CD24+CD38+ Bregs in IBCa patients compared with patients with benign tumor or healthy individuals." (PMID 27762298, 2016).
Colon polyp (1 paper, 2024). "Increased abundance of RuminococcaceaeUCG002 can cause increased levels of CD24 on IgD- CD38- B cells, which in turn leads to an increased risk of colon polyps." (PMID 39346904, 2024).
gastrointestinal disease (1 paper, 2022). A disease that occurs in the gastrointestinal system, excluding the hepatobiliary system. "Although the expression of CD38 may be a possible target for the therapy of gastrointestinal diseases, there are currently no data on the use of anti-CD38 antibodies in the therapy." (PMID 36077708, 2022).
gastrointestinal tract cancers (1 paper, 2024). "As a subtype of Naive B cells, IgD+ CD38- B cells are suggested, based on MR analysis, to have a causal relationship with three types of gastrointestinal tract cancers." (PMID 38533503, 2024).
CD38 also shares sentences with these, for which no sentence is quoted: T-cell acute lymphoblastic leukemia (11 papers); glioblastoma (5); hypertrophy (4); ulcerative colitis (4); endometrial cancer (3); myalgic encephalomyelitis (3); renal carcinoma (3); amyloidosis (2); ANCA-associated vasculitis (2); autoimmune hemolytic anemia (2); chronic periodontitis (2); Ebola (2); esophageal squamous cell carcinoma (2); graft versus host disease (2); head and neck cancer (2); idiopathic pulmonary fibrosis (2); invasive breast carcinoma (2); lymphoproliferative disorders (2); MALT lymphoma (2); metastatic tumors (2); monocytic leukemia (2); nephritis (2); neuromyelitis optica spectrum disorder (2); primary effusion lymphoma (2); prostate (2); pulmonary hypertension (2); respiratory infections (2); rheumatic diseases (2); schizophrenia (2); stomach cancer (2).
A further 129 diseases each share a sentence with CD38 in 1 paper.